CLDN4 (claudin 4)
Diseases named in the same sentence as CLDN4 in open-access papers (continued):
Sharing a sentence is not in itself a finding about the gene and the disease.
tumor (continued). "In both the primary tumor and the metastases, Claudin-4 was most frequently expressed, followed by GLUT-1, CAIX, EGFR and IGF1R." (PMID 25417118, 2014). "In the authors’ ultrastructal studies, an increase in tight junctions was found between neighboring claudin-4-overexpressing tumor cells." (PMID 25120725, 2014). "The expression level of claudin-4 was also significantly correlated with the tumor growth pattern (P < 0.001)." (PMID 23822740, 2013). "Re-expression of E-cadherin in the CLDN3 or CLDN4 knockdown cells reduced migration, invasion and tumor growth in vivo." (PMID 23805314, 2013). "We have shown that claudin-4 can also promote motility in cells that normally express claudin-4 and that both normal cells and different types of tumor cells all exhibit the same phenomenon." (PMID 23521713, 2013). "In the present study, immunohistochemical and PCR analysis of tumor xenografts demonstrated that cisplatin treatment is capable of producing a significant decrease in claudin-4 expression which correlated with the reduction in tumor volume." (PMID 23599806, 2013). "Because we have shown that the DFYNP peptide can target claudin-4 we treated tumor cells with the fluorescent mimic peptide at 4°C for one hour before washing the cells with ice cold PBS and subjecting them to immediate imaging." (PMID 23521713, 2013). "Among the claudin subtypes, the expression of claudin-4 is frequently altered in various tumor tissues." (PMID 23822740, 2013). "There is however concern that the expression of claudin-4 on normal epithelia will limit the usefulness of this anti-tumor strategy." (PMID 23685873, 2013). "The expression level of claudin-4 was significantly correlated with tumor differentiation (P < 0.001), gender (P = 0.003), age (P = 0.025) and tumor location (P = 0.033)." (PMID 23822740, 2013). "We reclassified patients with low expression of claudin-4 in the intermediate group as having the expanding type, and patients with high expression of claudin-4 as having the infiltrative type of tumor." (PMID 23822740, 2013). "With immunofluorescence, we found claudin-4 localized along cellular projections of both normal and tumor cells." (PMID 23521713, 2013). "A significant reduction of tumor growth and a significant decrease in claudin-4 expression were observed in the cisplatin group." (PMID 23599806, 2013). "In summary, we have shown that claudin-4 promotes both normal and tumor cell motility through key extracellular loop interactions." (PMID 23521713, 2013). "In primary tumours, claudin-4 was more highly expressed in lower grade (Gleason 6) lesions than in higher grade (Gleason ⩾7) cancers." (PMID 18648369, 2008). "On the other hand, the majority of the invasive tumour cells studied exhibited moderate staining (64%; 16 out of 25) for claudin-4, whereas 24% (6 out of 25) were strong and 8% (2 out of 25) low." (PMID 18648369, 2008). "CLDN4 mRNA was also found to be present in these 13 invasive tumours and surrounding mammary tissues using real time-PCR." (PMID 15743508, 2005). "The cytotoxic effect was dose dependent and was positively correlated to the levels of either claudin-3 or claudin-4 expression as tested by RT–PCR in tumor samples." (PMID 15785748, 2005). "Although it has shown impressive anti-tumor activity in preclinical mouse models, its potential clinical use may face obstacles due to CLDN4's widespread expression in many normal tissues, which raises concerns about possible toxicity in healthy tissues." (PMID 40057807, 2025). "CLDN4 upregulation enhances tumor microenvironment maintenance and stemness." (PMID 40687428, 2025). "Claudin-4 may also influence the permeability of the tumor microenvironment, facilitating cancer cell dissemination." (PMID 39869563, 2025). "The absence of Claudin-4 expression further supported the diagnosis of a mesenteric SMARCA2-deficient yet SMARCA4-preserved undifferentiated tumor." (PMID 40012963, 2025).
tumor (continued). "CLDN4 upregulation correlates with tumor invasion and metastasis." (PMID 40687428, 2025). "Western blot analysis demonstrated significantly elevated CLDN4 expression in tumour tissues." (PMID 41252335, 2025). "Importantly, cKM3907 (fused to a IgG1 Fc domain) also had CDC activity and prevented measurable tumor formation of CLDN3 or CLDN4 transfected Chinese hamster ovary (CHO) when injected into SCID mice." (PMID 38371623, 2024). "In this current cohort claudin-4 downregulation was not correlated with tumor grade, however positive claudin-4 expression was associated with a shorter DMFS." (PMID 39687048, 2024). "These KACs had increased expression of CDKN1A, CDKN2A, PLAUR and the tumour marker CLDN4." (PMID 38418883, 2024). "Moreover, the tumor growth in T47D:dKO:CLDN4:LXRβS432A xenograft was significantly reduced than that in T47D:dKO:CLDN4:LXRβ cells." (PMID 37059993, 2023). "Moreover, there was a significant relationship between CLDN4 expression and histological differentiation as well as tumour growth patterns." (PMID 38201579, 2023). "The barrier action of CLDN4 leads to the accumulation of angiogenic factors within the tumor microenvironment and may promote angiogenesis." (PMID 36982569, 2023). "Thus, in CLDN4-overexpressing epithelial malignancies, the barrier function of TJs serves to maintain the tumor microenvironment and retain tumor-secreted growth factors to promote the malignant cancer phenotype." (PMID 36982569, 2023). "This discovery contributes to our understanding of the role of claudin-4 in these conditions and provides valuable insights into the intricate molecular mechanisms that contribute to the compromised barrier function observed in these skin conditions." (PMID 38534263, 2023). "Studies have shown that Claudin-4 is highly expressed in various malignant tumors, suggesting that Claudin-4 may become a tumor marker and an emerging target for treatment." (PMID 37465316, 2023). "However, recent studies have revealed that CLDN4 is not only involved in cell adhesion but also in signal transduction, which plays an important role in the formation of cancer pathologies such as tumor initiation, progression, and metastasis." (PMID 36982569, 2023). "Furthermore, Claudin-4 expression in normal areas of the central nervous system (CNS) is negligible, which restricts apoptosis exclusively to brain tumor cells and hinders tumor growth." (PMID 36077843, 2022). "The unregulated expression of Claudin-4 (CLDN4) plays an important role in tumor progression." (PMID 35418179, 2022). "Epithelial makers (KRT18, KRT19, KRT17, KRT7, and CLDN4) were also highly expressed, indicating that M2 may be derived from transdifferentiation of epithelial cells in the tumor." (PMID 35265520, 2022). "Furthermore, an increased CLDN4 level correlates with tumor virulence through various mechanisms, including increased drug resistance by tight junction barrier function, increased EMT phenotype, and increased stemness." (PMID 35742959, 2022). "We demonstrated that high CLDN-4 expression is a potential predictor of synchronous neoplasms." (PMID 35743616, 2022). "Tumor cells were distributed in clusters and positive for Brg-1 and Claudin-4." (PMID 36275797, 2022). "Furthermore, defects in DNA repair and damage response genes such as RAD51, KU80 SIRT1, NFAT5, and REV3L, or ESCC tumor cells expressed higher CLDN4 to harbor stem-like properties are also the potential CCRT resistance mechanisms." (PMID 35457185, 2022). "Likewise, the positive protein expression of CLDN-4 was reported in correlation with larger tumor size of BrCa of Egyptian women." (PMID 33407452, 2021). "Similarly, blocking Cldn4 using a monoclonal antibody in ovarian and pancreatic xenograft mouse models inhibited tumor growth." (PMID 35006480, 2021). "Moreover, the role of claudin 4 in the development of chemoresistance by inhibiting access of therapeutic agents to tumor cells has been reported in several studies 31-33." (PMID 34522225, 2021).
tumor (continued). "Our findings showed a positive correlation between CLDN-4 expression and larger tumor size." (PMID 33407452, 2021). "A claudin-4 imaging agent might also be a useful tool for monitoring the effects of claudin-4–targeted therapies, which have shown promise in suppressing tumor growth in several preclinical cancer models." (PMID 32414951, 2020). "The feasibility of claudin-4–targeted tumor detection in vivo with wild-type versus mutant cCPE-based radiotracers was then assessed in immunocompromised mice bearing subcutaneous PSN-1 or HT1080 tumor xenografts." (PMID 32414951, 2020). "Thus, expression of CLDN4 is thought to be affected by the presence of bacteria within the tumor environment." (PMID 32064037, 2020). "CLDN4 expression index was associated with primary tumor (pT), nodal metastasis (pN), distant metastasis (pM) and pathological stage, but not with histological grade." (PMID 31498559, 2019). "Notably, CLDN4 expression levels were progressively reduced in tumor tissues of higher histological grades (i.e. those that exhibited lower levels of differentiation)." (PMID 31040910, 2019). "Furthermore, CLDN4 expression was inversely correlated with tumor invasion (pT), nodal metastasis (pN) distant metastasis (pM), and pathological staging (pStage)." (PMID 31040910, 2019). "Volume-of-interest analysis revealed that uptake of [111In]anti-claudin-4 within claudin-4-overexpressing Panc-1 tumours increased over time, yielding uptake values of 9.5 ± 1.9, 14.7 ± 3.0 and 16.9 ± 4.5 % ID/ml at 24, 48 and 72 h post-injection (p.i.), respectively." (PMID 28842811, 2018). "Tumour uptake of [111In]anti-claudin-4 mAb in Panc-1 xenografts at 72 h p.i. was markedly higher than the maximum value reported by Foss and co-workers in the same model (4 % ID/g at 48 h p.i.), probably due to the superior kinetic stability of the radioimmunoconjugate." (PMID 28842811, 2018). "However, overall tumour uptake was generally low, and we have since sought to investigate alternative claudin-4 targeting vectors with improved target affinity and specificity." (PMID 28842811, 2018). "Furthermore, [111In]anti-claudin-4 showed that moderate penetrative ability as radioactivity can be observed extending diffusely into the core of the tumours." (PMID 28842811, 2018). "Finally, our research showed that Claudin 1, Claudin 4, and Claudin 7 were closely related to tumour growth and metastasis." (PMID 28376864, 2017). "Moreover, the tumor volumes in the lncRNA overexpressing groups were larger than in the CLDN4 overexpressing group." (PMID 28819095, 2017). "It is possible, therefore, that the transmembrane claudin-4 protein may interact with key molecules near the tumor cell surface to prevent activation of the extrinsic apoptotic signaling pathway." (PMID 27724921, 2016). "An important question for future research is whether DFYNP acts by interfering directly with claudin-4 interactions with the extracellular matrix or by interfering with its interactions with other molecules that link tumor cells to the matrix." (PMID 27724921, 2016). "It is possible that the activity of claudin-4 in tumor cells may, in fact, stem from their function in the normal epithelium from which the tumor arises and this activity is enhanced due to loss of regulation." (PMID 27724921, 2016). "This group has examined claudin-4 activity in the 2008 tumor cell line." (PMID 27724921, 2016). "We have shown that claudin-4 can decrease tumor cell sensitivity to apoptosis." (PMID 27724921, 2016). "Additionally, Yin and colleagues have shown that CD44+ (high claudin-4) cells have an enhanced ability to migrate compared to the CD44- (low claudin-4) population of the same tumor." (PMID 27724921, 2016). "Our hypothesis is that claudin-4 interacts with molecules at the tumor cell surface through extracellular loop interactions and alters intracellular signaling pathways to promote tumor cell survival and migration." (PMID 27724921, 2016).
tumor (continued). "We showed that knockdown of either CLDN3 or CLDN4 substantially increased tumor growth and metastases, which prompted us to postulate that these two claudins may function to suppress EMT." (PMID 23805314, 2013). "As observed with claudin 1, claudin 4 was also more prevalent in the cytoplasm of the tumor cells." (PMID 23721519, 2013). "To test whether claudins, particularly claudin-4, could play a functional role in directing cell motility through extracellular interactions, we treated normal and tumor cells with the mimic peptide and examined changes in cell motility." (PMID 23521713, 2013). "We therefore wished to compare the claudin-4 positivity with CA125 values in our tumor panel." (PMID 19619303, 2009). "Although a moderate level of staining for claudin-4 was evident in the majority of invasive PCa cells, a closer examination of tumour sections revealed that claudin-4 expression tended to be higher in lower grade carcinomas compared with those of higher grades (Gleason 5) (data not shown)." (PMID 18648369, 2008). "Interestingly, lower grade (Gleason grade 3) tumours had higher staining for claudin-4 compared with higher grade (Gleason grade 5) tumours." (PMID 18648369, 2008). "However, before claudin-4 can be considered for any role in this regard despite its proclivity to be overexpressed preferentially in lower Gleason score tumours, further evaluation is essential." (PMID 18648369, 2008). "Furthermore, the absence of Claudin-4 expression led to the diagnosis of a Mesenteric SMARCA2-deficient yet SMARCA4-preserved undifferentiated tumor." (PMID 40012963, 2025). "Because an excessive oxidative stress response can lead to cell death and the nuclear lamina can protect against ROS, these data suggest that the claudin-4’s role in remodeling the nuclear architecture may help protect tumor cells during excessive oxidative stress response during olaparib treatment." (PMID 39625235, 2025). "This was expected as oncogene-enriched subtype tumours exhibited more aggressive tumour growth and had an increased expression of gene mutations involved in cell proliferation (ERBB2, SLC44A4, EPCAM, CLDN3, and CLDN4), cell differentiation (ELF3 and GPX2), and mucin production (KRT20)." (PMID 36723696, 2023). "D@C-LP NIRF signals at the tumor site were stronger than those of D@LPs, indicating much greater accumulation of D@C-LPs in tumors compared with D@LPs and supporting strongly enhanced targeting ability of C-LPs compared with LPs in this CLDN4-positive allograft model." (PMID 37237291, 2023). "Importantly, previous studies have shown that CLDN4 is involved in tumor EMT regulation." (PMID 35418179, 2022). "Interestingly, the results observed that 5 hub genes were shared in the GEO and TCGA profiles, including SLC44A3, DBF4, NAPSA, ATP6V0A4, and CLDN4, which were closely associated with B cells, CD4+ T cells, CD8+ T cells, Macrophage, Neutrophil, and Dendritic cells to involve in tumor immunity." (PMID 36325324, 2022). "In addition, over-expressed CLDN4 could partially reverse the effects of SPTBN2 knockdown on tumor progression." (PMID 34887379, 2021). "While these approaches have shown great potential for delineating claudin-4 expression in tumour tissue and precancerous lesions in vivo, CPE-based imaging agents suffer from poor solubility, unknown immunogenicity and exhibit only moderate affinity and specificity for claudin-4." (PMID 28842811, 2018). "Nevertheless, the poor contrast provided by [111In]anti-claudin-4 mAb in the KPC model could also be the result of limited access to the tumour mass due to the presence of dense fibrous stroma, as well as non-specific accumulation of the radioimmunoconjugate in the liver and spleen." (PMID 28842811, 2018).
tumor (continued). "This phenomenon might affect the relationship between CLDN4 expression and tumor progression (pT)." (PMID 30647838, 2018). "Thus, consistent with our in vitro findings, we further found that the effect of CLDN4 on increasing tumor proliferation could be rescued by miR-596 or miR-3620-3p and enlarged when lncRNA-KRTAP5-AS1 or lncRNA-TUBB2A were overexpressed in the nude mouse model." (PMID 28819095, 2017). "Claudin-4 negative to positive conversion in the metastases was significantly associated with tumor size (p = 0.015; 11/14 versus 31/72), whereas negative to positive conversion of EGFR was associated with negative PR status (p = 0.046; 8/8 versus 46/75) and high MAI (p = 0.047; 8/8 versus 47/75)." (PMID 25417118, 2014). "Similarly, the tumor suppressive role of claudin-4 has been described in various cancers." (PMID 24009024, 2013). "The correlation between the expression of claudin-4 and the change in tumor volume due to chemotherapy demonstrates that therapeutic inhibition of claudin-4 may reduce claudin-expressing cells and it further suggests a role of claudin-4 as a marker for the activity of anti-neoplastic agents." (PMID 23599806, 2013). "Similarly, CLDN4 was elevated in tumors of the lung, breast, stomach, pancreas, and ovary." (PMID 16836752, 2006). "CLDN4 is embedded in tight-junction/ECM pathways and is in a tumor-enriched WGCNA neighborhood that aligns with cancer invasion-competent adhesion states." (PMID 41614938, 2026). "After the observation, tumours were harvested from each group, and IHC of CK7, CLDN4 and Ki‐67 was conducted." (PMID 41252335, 2025). "Focused on this cluster number “3”, cells from the three samples were found to express some epithelial/tumor markers at distinct levels, with markers including EPCAM, CD44, KRT8, ITGA6, and CLDN4." (PMID 41440935, 2025). "All groups showed high expression levels of CK7 and CLDN4, confirming the epithelial origin and the potential to be targeted by NESC of the tumours." (PMID 41252335, 2025). "Downregulated were the critical genes CAV1, VWF, and DCN, suggesting loss of tumour-suppressive functions, and upregulated were SCGB2A1, CLDN4, and immune-related genes CCL3 and GZMB, promoting tumour growth and immune evasion." (PMID 41312167, 2025). "The tumor cells also typically show negativity or only focal positivity for other epithelial markers like cytokeratin, EMA, and claudin-4, as well as mesenchymal markers such as CD10." (PMID 40826772, 2025). "In our tumor epithelial dataset, genes with the strongest positive correlation with TM4SF1 expression within the HV tumor cells were EMP1, CLDN4, EZR, and KRT19." (PMID 40527915, 2025). "GFP expression was almost exclusive to alveolar regions and tumours, the latter of which were almost entirely GFP+ as well as KRT8+ and KAC marker-positive (CLDN4+CAVIN3+)." (PMID 38418883, 2024). "The use of in vitro and in vivo models has demonstrated that targeting CLDN1, CLDN3, CLDN4, CLDN6 and CLDN18.2 consistently reduces tumor burden across a multitude of different cancer types, with specific intra-tumoral accumulation and low rates of AEs." (PMID 38371623, 2024). "We also verified the positive correlation between ID1 expression and SOX9 (p = 6.90e‐05, r = 0.20), EPCAM (p = 5.37e‐06, r = 0.23), CD24 (p = 1.82e‐07, r = 0.27), and CLDN4 (p = 6.04e‐05, r = 0.18) expression in HCC tumor tissue from TCGA datasets." (PMID 37085918, 2023). "Here, we suggest another ligand-receptor binding strategy for targeted chemotherapy that utilizes claudin-4 (CLDN4), a receptor that is inaccessible in the normal environment but is exposed in a tumor environment." (PMID 37237291, 2023). "A tumour-suppressive function of CLDN1, 4, and 11 has been indicated for GC, while this function of CLDN4 has been indicated in the pathogenesis of PC." (PMID 38201579, 2023).